RNU6-1113P (RNA, U6 small nuclear 1113, pseudogene)
Gene: Small nuclear RNA gene on chromosome 6 (43,474,186 to 43,474,292, forward strand). Ensembl gene ENSG00000207076.
Homologues: Orthologues: chimpanzee U6 (98% identical), macaque U6 (95% identical). Paralogues in human: RNU6-949P (89% identical), RNU6-11P (87% identical), RNU6-24P (87% identical), RNU6-37P (87% identical), RNU6-1060P (86% identical), RNU6-116P (86% identical), RNU6-1181P (86% identical), RNU6-12P (86% identical), RNU6-13P (86% identical), RNU6-32P (86% identical), RNU6-33P (86% identical), RNU6-34P (86% identical), and 1287 more.